TLR2 (toll like receptor 2)
Diseases named in the same sentence as TLR2 in open-access papers (continued):
Sharing a sentence is not in itself a finding about the gene and the disease.
infection (continued). "A study investigating the involvement of TLR2, TLR4, and MyD88 in pulmonary C. burnetii infection found a different role for these factors according to the site of infection." (PMID 34796128, 2021). "In regulating microbe-elicited ROS production during an antimicrobial response, many studies showed that host PRRs (mainly TLR2, TLR4, NOD2, NLRX1, and NLRP3) and redox modulation alleviated pathogen infection." (PMID 34299310, 2021). "The expression of IL-1β, IL-6, IL-8, IL-18, TNF-α, MMP-9, RANKL, TLR-2, TLR-4, TLR-6, thymic stromal lymphopoietin (TSLP), and ICAM-1 was evaluated by qPCR at 2 and 24 h after infection." (PMID 33802988, 2021). "Previous studies have shown the importance of macrophage TLR2 activation for the secretion of IL-1β, IL-6, TNF-α, IFN-β during the infection with L.m." (PMID 34194428, 2021). "In fact, in case of an infection by C. glutamicum ATCC13032, C. ulcerans KL756 and C. silvaticum W25, TLR2 activation was also observed." (PMID 33805570, 2021). "MUC1 also inhibits signaling of other TLRs, including TLR2, TLR4, TLR7, and TLR9, during infection with respiratory syncytial virus." (PMID 33184103, 2020). "Using TLR transfected HEK-293 reporter cells, we have shown that P. histicola infection induced TLR2 signalling (at 4 hours) and importantly a rapid induction in TLR5 signalling, which was significantly reduced by the end of the 4 hour infection period." (PMID 33031374, 2020). "Then, pro-inflammatory immune response induced in RAW 264.7 cells by TLR2 and TLR4 agonists favors the uptake of C. gattii promoting a control of growth of yeast in the early stage of infection." (PMID 33304649, 2020). "A previous study showed that TLR2 and TLR4 were expressed in tissue infected with Nocardia during the early stages of infection." (PMID 31964749, 2020). "Altogether, our data provided evidence for the critical and dual role of TLR2 in DENV infection and infection-mediated immune responses." (PMID 32576819, 2020). "The roles of TLR2 during natural HSV infection are unclear, with evidence suggesting that TLR2 is important for controlling infection but also that TLR2 activation increases immunopathology in mouse models of HSV infection and pseudorabies virus infection." (PMID 33027661, 2020). "The avirulent S. Typhimurium ∆rfa mutants are potentially useful for modulation of the TLR2 and TLR4 signaling pathways to protect the immunocompromised gnotobiotic piglets against subsequent infection with the virulent S. Typhimurium." (PMID 32842482, 2020). "Here, we observed that inhibition of both TLR2 and TLR4 signaling with OxPAPC resulted in significantly higher retained retinal function after infection with the WT strain, likely due to the preserved retinal architecture in these eyes." (PMID 32117322, 2020). "The activation of RAW 264.7 cells induced by TLR2 and TLR4 agonists favored the phagocytosis of C. gattii and inhibited the growth of yeast in the early period of infection." (PMID 33304649, 2020). "A previous study reported that TLR2 KO mice displayed increased lung concentrations of MCP-1 and MIP-2 after infection with A. baumannii." (PMID 33329595, 2020). "Then, we showed a lower level of CXCL1 and CCL3 in TLR-2KO and TLR-4KO peritoneal lavage, suggesting that TLR-2 and TLR-4 are important to chemokine production by resident cells in the infection site." (PMID 33193308, 2020). "The functional analyses uncovered the ability of TLR2/6/CD14 to sense DENV infection and to drive infection-mediated inflammatory responses leading to activation of human vascular endothelium." (PMID 32576819, 2020). "The exact mechanisms governing TLR2 expression following DENV sensing and/or infection remain to be elucidated and will be the focus of our future studies." (PMID 32576819, 2020).
infection (continued). "Then we compared the expressions of RLRs and TLRs after infection, and found that the expressions of MDA5 were much higher than RIG-I, while the expressions of TLR3 was much higher than those of TLR2 and TLR4." (PMID 31947624, 2020). "Wild type (WT), TLR2 knockout (KO), TLR9 KO, and caspase-1 KO mice were examined at various intervals post-infection to quantify bacterial burden, leukocyte recruitment, and inflammatory mediator production in the galea, brain, and bone flap." (PMID 32290861, 2020). "However, much less is known about the relationship between TLR2 and S. aureus in human monocytes, although this cell type likely contributes significantly to the host response to S. aureus during bloodstream infection, where these cells are first line responders to infection." (PMID 31558608, 2019). "Primary porcine microglial cells decrease their expression of NPY when treated with TLR2 agonists, indicating that microglial cells are involved in the altered expression of NPY after SE infection." (PMID 31803186, 2019). "These responses eliminate invading pathogens in the very early phase of infection, implying that there is a crucial role for FL-WRS as an endogenous ligand of human TLR2/4 in countering infections and immune regulation 20,50." (PMID 30613102, 2019). "So far, these results indicate that in human CL, in addition to TLR2 and TLR4 are preferentially expressed in intermediate monocytes, the infection with L. braziliensis increases the expression of these receptors on this monocyte subset." (PMID 31119102, 2019). "First, we showed that after infection with L. braziliensis there is an increase in TNF expression and it occurs predominantly in TLR2 (+) and TLR4 (+) cells." (PMID 31119102, 2019). "Several lines of evidence have suggested that Mtb infection can recognize TLR-2 in producing pro-inflammatory signals, and thus TLR-2 serves as a protective factor against infection." (PMID 30717477, 2019). "To characterize the effect of tlr2 mutation in the absence of infection, we compared the transcriptome of homozygous mutant larvae with that of heterozygote larvae, thereby excluding the effect of non-dominant background polymorphisms that might have resulted from ENU mutagenesis." (PMID 31747871, 2019). "Given the importance of MIC1 and MIC4 as lectins that engage TLR2 and TLR4 N-glycans to induce increased levels of IL-12 release during T. gondii in vitro infection, we investigated the biological relevance of these proteins during in vivo infection." (PMID 31226171, 2019). "Because the ex vivo expression of these receptors was higher on inflammatory monocytes from CL patients, further experiments evaluating the expression of TLR2 and TLR4 on monocyte subsets after infection with L. braziliensis were performed." (PMID 31119102, 2019). "A recent study reported that ROS levels in microglia are increased after infection with HSV-1 and that this process is dependent on Toll-like receptor 2 (TLR2) and p38 MAP kinase, as well as ERK1/2 signaling pathways." (PMID 30863282, 2019). "The expression of TNF-α, IL-12p70, and IL-10 was induced by MAH-infected DCs exposed to LPS in the same manner as LPS-alone treatment in TLR2−/− and as MAH-alone infection in TLR4−/−." (PMID 31440223, 2019). "Therefore, it appears that TLR2 signaling in the brain might contribute to the control of parasite growth, but not to brain pathology or the impaired fear memory response induced by infection with T. gondii." (PMID 31404078, 2019). "Toll-like receptors, such as TLR2, TLR3, TLR7, and TLR9 have been described to mediate antiviral activities against HSVs during infection." (PMID 31114761, 2019). "We observed upregulation of TLR2, TLR4, and downregulation of TLR10 at the chronic stages of infection." (PMID 31555289, 2019). "We also evaluated the expression of TLR2 and TLR4 on monocytes from HS after infection with L.braziliensis." (PMID 31119102, 2019).
infection (continued). "First, the TLR2+/+ and TLR2-/- mice were infected with the T. gondii PLK strain, and their bodyweights were measured daily for 4 weeks after infection." (PMID 31404078, 2019). "During infection, toll-like receptor 4 (TLR4) and toll-like receptor 2 (TLR2) recognize gonococcal PAMPs and consequently activate the downstream inflammatory signaling cascade in immune cells." (PMID 31417575, 2019). "The level of IL-10 expression was similar in that in MAH/LPS-infection and LPS-treatment of TLR2−/− DCs and in MAH/LPS-infection and MAH-infection of TLR4−/− DCs, whereas IL-10 production was strongly increased in MAH/LPS-infection in WT DCs." (PMID 31440223, 2019). "The aim of this study was to determine the expression of TLR2 and TLR4 in the eyes of mice following intranasal infection with Acanthamoeba spp." (PMID 31309100, 2019). "And infection of macrophages with the three ΔsurA/SCV1, Δslp/SCV1, and ΔlpoB/SCV1 mutants led to significantly decreased expression of TLR2, TNF-α, IL-1β, and IL-6 compared with those detected in the SCVs." (PMID 29594069, 2018). "In a murine model of infection, S. aureus has been shown to evade TLR2 activation by secreting SSL3, indicating that TLR2 inhibition is important for staphylococcal pathogenesis." (PMID 30111706, 2018). "Moreover, sustained systemic exposure to a TLR2 agonist protects mice from systemic C. albicans infection, and leads to an expansion of spleen HSPCs and myeloid cells; this protection is abrogated by immunodepletion of expanded HSPCs, indicating their protective role against infection." (PMID 30234030, 2018). "The UdLAMPs of both Ureaplasma stimulated the gene expression of IL-1β, TNF-α, TLR2 and TLR4 after 6 and 12 h following infection in macrophages." (PMID 30050519, 2018). "The known recognition of TLR2/CD14 N-glycans on innate immune cells by ArtinM is essential for inducing Th1 cytokine production, which favors the host immune response against infection by intracellular pathogens." (PMID 30216978, 2018). "Therefore, the observed opposite responses of HSPCs to Pam3CSK4, switching from tolerance (one dose) to training (extended exposure), cannot be related to pathogen load, as the response to Pam3CSK4 involves only one PRR (TLR2) and occurs in the absence of deleterious effects associated to infection." (PMID 30234030, 2018). "In vivo studies confirmed the critical role that TLR2 and TLR4 play in infection-induced peritoneal inflammation and fibrosis." (PMID 30538643, 2018). "Taking into account these data, in our model of extended TLR2 agonist treatment, mice were given 500 μg of ACK2 or its isotype control, by intraperitoneal injection, at day 4 (48 h before infection)." (PMID 30234030, 2018). "We observed increased numbers of infected macrophages during the course of infection in TLR4−/− macrophages, and an increased rate only after 48 h of infection of TLR2−/− macrophages." (PMID 30555476, 2018). "During infection by L. (L. ) donovani, on the other hand, p38 MAPK activation is mediated by TLR2, lowering IL-12 production while increasing IL-10 production." (PMID 29543867, 2018). "The results illustrated that TLR2, TLR4 and TLR9 were up-regulated by over 300% in HEC-1-A cell 24 h post-infection (p.i.), and only TLR4 transcription was enhanced by over 700% in VK2 cells." (PMID 30419930, 2018). "And infection of macrophages with the three ΔsurA/SCV1, Δslp/SCV1, and ΔlpoB/SCV1 mutants led to significantly decreased expression of TLR2, TNF-α, IL-1β, and IL-6 compared to those detected in the SCVs." (PMID 29594069, 2018). "Here, we reported the roles of TLR2, TLR4, and the adaptor molecule MyD88 in mediating the phagocytosis of L. amazonensis and conferring resistance to infection, in contrast to the higher infectivity index observed in the absence of those molecules." (PMID 30555476, 2018).
infection (continued). "Transcriptional levels of neutrophil TLR2 and TLR4 at 3 h post-infection with SS2 ZY05719 were 2.9- and 2.5-fold that of untreated neutrophils, whereas that of TLR6 was unchanged." (PMID 30581435, 2018). "In summary, in situations of cellular stress or upon infection, the DAMP eRNA serves a prominent cofactor role in facilitating PAMP-mediated activation of TLR2." (PMID 29261777, 2017). "In this study, we comparatively analysed the developing processes of C. sinensis and the iNOS/NO responses in TLR2 wild-type and mutant C57BL/6 J mice after the infection." (PMID 28784165, 2017). "Our results showed the intestinal fluids of TLR2−/− mice produced significantly more IL-12 p40 and IFN-γ, while significantly less IL-4 was produced during the early stage of infection (5 dpi) compared with WT mice." (PMID 28979269, 2017). "During infection, both the percentage and the mean fluorescence intensity (MFI) of TLR2 expression on CD11c+ cells were increased." (PMID 28280488, 2017). "In cattle, mRNA levels of TLR2 and TLR4 were increased following infection of bovine intestinal epithelial cells with C. parvum, whereas the expression of TLR1, TLR3 and TLR5-TLR10 were unchanged." (PMID 28800747, 2017). "Enhanced infection was inversely seen with dilution factors of anti-DenV2 sera obtained from BL/6, TLR2 KO, and MyD88 KO mice, which indicates that anti-DenV2 sera from BL/6, TLR2 KO, and MyD88 KO mice could increase the infectivity of DenV2 and DenV4 in FcγR-bearing macrophages." (PMID 29285314, 2017). "In vivo experiments in chickens further confirmed the observed inflammatory and innate responses induced by vvIBDV in DT40 cells in vitro, and IL-1β, IL-18, TLR1, TLR2, and TLR3 are the predominant DE genes after vvIBDV infection." (PMID 28086922, 2017). "Upon infection with L. interrogans serovar Copenhageni strain Fiocruz L1-130, IFN-γ mRNA is expressed in the organs of mice 3 days post-infection through a TLR2- and TLR4-dependent pathway." (PMID 28270811, 2017). "To investigate the effects of CCM111 on infection-mediated signaling, we further investigated the effects of CCM111 on the TLR2, TLR3 and TLR4 signaling pathways using stable cells and luciferase reporter assays." (PMID 28687744, 2017). "In TLR2/9−/− mice TG large amount of granzyme B was produced by NK T, NK and CD8+ cells after infection." (PMID 28222752, 2017). "In this context pattern recognition receptors like TLR2, TLR4 and NLRP3 but also oxidative stress and antioxidant responses that are also responsible for infection defense play an important role." (PMID 30402600, 2017). "In this study, we found a significant and consistent increase in TLR2, TLR4, and TLR9 transcripts in the brains of lethally infected mice at days 6 and 10, as well as in brains of sublethal infection." (PMID 28742087, 2017). "During Schistosoma japonicum infection, TLR2 and TLR4 promoted opposite adaptive immune responses, including T cell activation and cytotoxic gene expression, which led to different infection outcomes." (PMID 28784165, 2017). "Since TLR2 and TLR4 are involved in the recognition of Leishmania by neutrophils, it is meaningful that infection with L. major promotes CD14 internalization in neutrophils." (PMID 28187163, 2017). "Quantitative reverse transcription-PCR data showed that 30 min post PAO1 infection, transcriptions of all tested NF-κB-dependent genes, including IL-1α, IL-1β, IL-6, IFN-γ, MCP-2, MIP1α, TNF-α and TLR2, were significantly increased in Lyn-silenced MH-S cells." (PMID 29263906, 2016). "We have found that TLR2 and TLR4 cooperate in the early control of this infection, while TLR9 is dispensable." (PMID 28119856, 2016). "There are many studies evaluating the relationship of CD14, TLR2, and TLR4 in various infections of adults." (PMID 27252945, 2016). "The highest TLR2 and TLR4 expression levels were at 2 dpi, decreasing during the time of infection and reaching a minimum at 30 dpi." (PMID 27511368, 2016).
infection (continued). "Intracellular infection with the S. aureus WCH-SK2WT elicited a more consistent innate immune response in comparison to intracellular S. aureus WCH-SK2SCV infection with an increased expression of IL1B, IL6, IL12, MMP9, and TLR2 at 24 h." (PMID 28083514, 2016). "Although we demonstrated that TLR2 and TLR4 expression is regulated during E. chaffeensis infection, it is possible that other TLRs can also be regulated by the Notch signaling during infection." (PMID 27381289, 2016). "This process required the PCN033 infection-induced upregulation of VEGFA and Snail-1, which involves the activation of TLR2-MAPK-ERK1/2 signaling cascade." (PMID 27588479, 2016). "We have now analyzed the role of TLR2, TLR4 and TLR9 in the control of B. microti infection and found that in vivo TLR2 and TLR4 cooperate to eliminate this pathogen, while TLR9 is dispensable to control the infection." (PMID 28119856, 2016). "Activation of TLR2 and TLR4 along the time course of the experimental infection triggered early intestinal (innate) immune response at 1 and 2 dpi." (PMID 26738723, 2016). "Ara-LAM treatment significantly augmented the expression of TLR2 in splenic CD8+ T-cells on 14 and 28days post infection." (PMID 26559815, 2015). "In order to investigate the effect cellular TLR2 expression has on host innate responses to HIV-1 proteins and infection, we initially set out to utilize the well-characterized HIV-1 luciferase reporter assay, TZMbl cell line." (PMID 26347747, 2015). "Peritoneal infection by Enterococcus faecium is sensed predominantly by macrophages via TLR2 which then secrete IL6, TNF-α, MIP-2, and KC during early infection." (PMID 26172831, 2015). "Side-by-side infection experiments using AD169 WT and AD169 miR-UL112-3p KO in fibroblasts revealed that both viruses induce TLR2 with similar efficiency at 1dpi." (PMID 25955717, 2015). "Since an MOI of 100 and 1 h infection time resulted in a reasonable percentage of infected macrophages for analysis by FACS, wild type, TLR2-/- and MyD88-/- macrophages were infected with GFP expressing E99 (E99GFP) under these conditions." (PMID 26317438, 2015). "Next, we infected TLR2 stably transformed cell line, TZMbl-2 and TZMbl with HIV-1 and evaluated viral DNA at 8 h post infection." (PMID 26347747, 2015). "Our results suggest that TLR1 and TLR6 mediate the innate immune response to M. haemolytica while TLR2 and TLR4 mediate response to infection by IBR and other viruses." (PMID 26121276, 2015). "Using the endothelial cell line b.End5, Robertson and coworkers have furthermore indicated that ATP release induces the expression of Toll-like receptor-2 (TLR2) and production of IL6 upon infection with S. epidermidis." (PMID 26424967, 2015). "TLR2, combination 1 (TLR3 ON and SHP2_T OFF), and combination 2 (TLR3, MKP_T ON and SHC_T OFF) mostly lead to the infection-free attractor (...110...) similar to the uninfected scenario." (PMID 26660865, 2015). "Transcription of TLR2 and TLR9, together with FoxP3, were all up regulated in the earlier stages of infection when compared with the controls." (PMID 26465878, 2015). "The increased expression of TLR2 and TLR4 by the Treg cells results in increased IL-10 which can play an immunotolerogenic role during the infection." (PMID 26635448, 2015). "We found reduced frequency of Tregs in Tlr-2−/− mice compared to WT mice infiltrating the draining lymphnodes and MOIL during infection." (PMID 25790134, 2015). "The expression of IE1–72, TLR2, TLR4, NF-κB and TNF-α mRNA was quantified at different time points prior to and following infection." (PMID 25435993, 2015). "Following the infection of SW480 cells, the mRNA levels of TLR2 and TNF-α increased gradually from 6 h, peaked at 48 h, and then decreased gradually." (PMID 25435993, 2015). "Soluble forms of TLR2 and TLR4 dampen the host immune response against infection by preventing the activation of TLR-mediated signaling." (PMID 24695582, 2014).